CEP55 (centrosomal protein 55)
Description:
Plays a role in mitotic exit and cytokinesis. Recruits PDCD6IP and TSG101 to midbody during cytokinesis. Required for successful completion of cytokinesis. Not required for microtubule nucleation. Plays a role in the development of the brain and kidney.
Synonyms: C10orf3; URCC6; FLJ10540; CT111; MARCH
Tractability: PROTAC: ubiquitination databases record sites on it.
Gene: Protein-coding gene on chromosome 10 (93,496,579 to 93,529,094, forward strand). Ensembl gene ENSG00000138180.
Subcellular location: Cytoplasm; Cytoplasm, cytoskeleton, microtubule organizing center, centrosome, centriole; Cytoplasm, cytoskeleton, microtubule organizing center, centrosome; Cleavage furrow; Midbody, Midbody ring; Midbody
Subcellular location (Human Protein Atlas): Centriolar satellite; Plasma membrane; Connecting piece; Cytosol; Midbody; Primary cilium; Principal piece
Gene Ontology:
Molecular function: identical protein binding; protein binding
Biological process: cranial skeletal system development; establishment of protein localization; midbody abscission; mitotic cytokinesis; mitotic metaphase chromosome alignment; nucleus organization; regulation of phosphatidylinositol 3-kinase/protein kinase B signal transduction
Cellular component: centrosome; cleavage furrow; cytoplasm; cytosol; Flemming body; membrane; midbody; centriole
Genetic constraint (gnomAD): Loss-of-function variants: 50 observed, 55.62 expected, observed/expected ratio (o/e) 0.9, 90% interval 0.71 to 1.14. The upper end of that interval is the gene's LOEUF score, 1.14, which puts it in group 4 of 6, group 1 being the genes least tolerant of losing a copy. Missense variants: 421 observed, 497.2 expected, observed/expected ratio (o/e) 0.85, 90% interval 0.78 to 0.92. Synonymous variants: 168 observed, 188.24 expected, observed/expected ratio (o/e) 0.89, 90% interval 0.79 to 1.01.
Homologues: Orthologues: chimpanzee CEP55 (99% identical), macaque CEP55 (97% identical), rabbit CEP55 (89% identical), pig CEP55 (87% identical), dog CEP55 (87% identical), rat Cep55 (76% identical), guinea pig CEP55 (75% identical), mouse Cep55 (75% identical), zebrafish cep55l (37% identical), tropical clawed frog cep55 (31% identical).
Diseases named in the same sentence as CEP55 in open-access papers:
CEP55 is named in the same sentence as 108 diseases in open-access papers, as found by Europe PMC text mining. Sharing a sentence is not in itself a finding about the gene and the disease. The quoted sentences say what the papers report.
breast carcinoma (56 papers, 2009 to 2025). "Among these hub regulators, we focused on CEP55, which was the most significantly upregulated and was associated with the shorter overall survival time in breast cancer." (PMID 34055036, 2021). "We recently reported that CEP55 overexpression causes premature exit during perturbed mitosis and is determinant of aneuploid breast cancer cell survival." (PMID 33087841, 2020). "In breast cancer patients, high-level expression of CEP55 associates with chemotherapeutic resistance, particularly to docetaxel." (PMID 35582716, 2019). "CEP55 (centrosomal protein 55) is responsible for cytokinesis, and its overexpression is associated with a genetic instability characteristic of breast cancers." (PMID 31756998, 2019). "Loss of CEP55 sensitizes breast cancer cells to anti‐mitotic agents through premature CDK1/cyclin B activation and CDK1 caspase‐dependent mitotic cell death." (PMID 30108112, 2018). "In breast cancer, CEP55 expression has been linked to docetaxel resistance." (PMID 38596293, 2024). "We found that CEP55 mRNA expression is associated with the PAM50 breast cancer molecular subtypes (Luminal A, Luminal B, HER2, and basal‐like), with the basal‐like subtype exhibiting significantly higher expression of CEP55 compared to other subtypes (P < 0.0001; Fig EV1A, available online)." (PMID 30108112, 2018). "Collectively, these data provide compelling evidence that high expression of CEP55 mRNA is associated with poor clinical outcomes in breast cancer and therefore could be a novel target for therapeutic intervention." (PMID 30108112, 2018). "CEP55, a centromere protein, has been shown to be overexpressed in various human cancers, including liver cancer, breast cancer, and renal cell carcinoma." (PMID 40771801, 2025). "Conversely, increasing the expression of CEP55 significantly boosted breast cancer cell proliferation and migration." (PMID 40723362, 2025). "In this study, we show that a high CEP55 level increases the CIN rate in OvCa and in breast cancer cells and our results from cellular and biochemical experiments indicate that CEP55 controls CIN by regulating MT stability." (PMID 39195269, 2024). "Conversely, knockdown of CEP55 expression reduces breast cancer cell proliferation, and following mitotic arrest by anti-mitotic drugs CEP55 increases cell death while reducing mitotic slippage." (PMID 38596293, 2024). "For instance, MiR-144, a tumor suppressor, inhibits cell viability, invasion and cell migration by downregulating CEP55 and induces apoptosis and cell cycle arrest in breast cancer." (PMID 36755291, 2023). "A search of the UALCAN database revealed that CEP55 was significantly highly expressed in breast cancer, especially in triple-negative breast cancer (TBNC)." (PMID 37887301, 2023). "Knockdown of CEP55 reduced the proliferation, invasion, and migration of breast cancer cells, thus exerting the tumorigenic effect of CEP55." (PMID 37887301, 2023). "In breast cancer cells, CEP55 knockdown significantly decreased cell survival, proliferation, and migration, while overexpression of CEP55 significantly promoted breast cancer cell proliferation and migration." (PMID 37887301, 2023). "To explore the molecular biological function of CEP55, we selected breast cancer for in vitro validation analysis." (PMID 37887301, 2023). "CEP55 peptides are naturally present in breast cancer cells and can induce an increase in antigen-specific cytotoxic T lymphocytes (CTLs)." (PMID 37484531, 2023). "For example, MEK1/2 inhibition was proposed as one possible perturbation approach as the MAPK pathway transcriptionally controls CEP55 expression in breast cancer cells." (PMID 37381005, 2023). "Our analysis showed that CEP55 was remarkably upregulated in the advanced stage of breast cancer compared to the stage I breast cancer sample." (PMID 34055036, 2021).
breast carcinoma (continued). "A similar expression profile of CEP55 has also been indicated in multiple types of cancers, including non–small‐cell lung cancer and breast cancer." (PMID 33417281, 2021). "Over the past decade, some studies have identified the role of CEP55 in many cancers such as breast cancer, colon cancer, and oral cavity squamous cell carcinoma and found that this protein is involved in cell cycle regulation." (PMID 34104194, 2021). "miR-144 as reported is down-regulated in breast cancer, and overexpressing miR-144 can negatively function on cell invasion and migration through reducing CEP55." (PMID 32355466, 2020). "Compared to normal tissues, CEP55 expression was extremely higher in most common tumor tissues, such as breast cancer, liver cancer, colorectal cancer, and gastric cancer." (PMID 32337246, 2020). "Centrosome protein CEP55 was found to have a role in promoting mitotic slippage, which again is mediated by the Bcl2 family proteins in breast cancer." (PMID 35582716, 2019). "To investigate this in a more clinically relevant context, we analyzed the relationship between CEP55 expression and survival in breast cancer patients treated with chemotherapy (variable treatments) using KMPlotter datasets." (PMID 30108112, 2018). "Knockdown of CEP55 in breast cancer cells in vitro significantly reduced the number of aneuploid cells, induced cell death during perturbed mitosis, and sensitized cells to anti‐mitotic agents." (PMID 30108112, 2018). "We identified high levels of CEP55, a cytokinesis regulator, promote survival of aneuploid breast cancer cells." (PMID 30108112, 2018). "Collectively, these data suggest that CEP55 overexpression confers anchorage‐independent growth and a survival advantage to breast cancer cells." (PMID 30108112, 2018). "In this study, we provide the first experimental evidence directly linking CEP55‐dependent aneuploidy to breast cancer survival." (PMID 30108112, 2018). "Our data demonstrated a role of CEP55 in aneuploidy tolerance, since knockdown of CEP55 in breast cancer lines resulted in elimination of aneuploid population." (PMID 30108112, 2018). "This study provides experimental evidence that targeting a specific cellular phenotype driven by potent oncogenes such as CEP55 indeed can be utilized for killing aggressive breast cancers with aberrant DNA contents." (PMID 30108112, 2018). "Here, we provide the first detailed description of CEP55's role in promoting genomic instability in breast cancer." (PMID 30108112, 2018). "Evidence presented here shows this is likely because it promotes genomic instability and resistance to anti‐mitotic drugs—even partial knockdown of CEP55 was sufficient for aneuploid breast cancer cell elimination in vitro." (PMID 30108112, 2018). "Consistent with this, we found that even partial silencing of CEP55 in aggressive basal‐like breast cancer cell lines eliminated their aneuploid subpopulations as a response to mitotic cell death, while allowing near‐diploid cells to survive in culture." (PMID 30108112, 2018). "Aberrant expression levels of the CEP55 genes are known to serve as prognostic marker of the estrogen receptor (ER) positive breast cancer." (PMID 28362316, 2017). "Consistently, bioinformatics analysis of published microarray data in FOXM1B-knockdown (by siRNA) breast cancer cells showed significantly decreased levels of CEP55." (PMID 19287496, 2009). "Likewise, in breast carcinoma, suppressing the expression of CEP55 by knockdown strategies significantly reduced cell viability, growth, and migration." (PMID 40723362, 2025). "In this study, we elucidated the function of CEP55 in the ferroptosis of breast cancer (BC)." (PMID 39871389, 2025). "Indeed, CEP55 has been described to be aberrantly expressed in many cancers, such as breast cancer and HCC, where its overexpression was considered to promote CIN." (PMID 37381005, 2023).
breast carcinoma (continued). "In this study, we verified the biological role of CEP55 in breast cancer cells, and the results showed that inhibition of CEP55 significantly reduced the proliferation rate of TNBC cell lines MDA-MB-231 and CAL-148, further reducing the migration and invasion of TNBC cells." (PMID 37887301, 2023). "CEP55 overexpression is validated to facilitate the malignant phenotypes of cancer cells in diverse tumors, including hepatocellular carcinoma, esophageal squamous cell carcinoma, renal carcinoma, glioma, breast cancer and NSCLC." (PMID 35549631, 2022). "We next analyzed the expression of CEP55 in breast cancer based on subclasses." (PMID 34055036, 2021). "CEP55 is upregulated when the MEK1/2‐MYC pathway is activated in breast cancer cells and is essential for breast cancer cell aneuploidy, proliferation, and survival, and CEP55 overexpression in primary breast tumor tissues is a marker for chromosomal instability and poor prognosis." (PMID 33497018, 2021). "Studies have shown that CEP55‐derived peptides may facilitate vaccination strategies for breast cancer and colorectal carcinoma." (PMID 33497018, 2021). "Likewise, when Cep55 was constitutively knocked down in TCLs, we found a significant reduction in >4n subpopulations, suggesting that Cep55 overexpression contributes to cancer cells ability to tolerate aneuploidy by us for breast cancer cells." (PMID 33087841, 2020). "CEP55 upregulation was previously reported to promote the migration and invasion of tumor cells and is related to the dismal prognosis for lung cancer, breast cancer, oral squamous cell carcinoma, cervical cancer, and osteosarcoma." (PMID 32337246, 2020). "Consistently, miR-144 targets and negatively regulates CEP55 in breast cancer." (PMID 33256799, 2020). "In addition, we discovered six genes: CCNE1, CEP55, EGFR, EXO1, FGFR4, and MAPT associated with both types of breast cancer." (PMID 32724790, 2020). "Moreover, overexpression of CEP55 accelerates the cell cycle transition in gastric cancer, and low expression of CEP55 inhibits cell growth in breast cancer and gastric cancer." (PMID 32587798, 2020). "Importantly, in our previous study in breast cancer, we have shown that CEP55 overexpression protects aneuploid cells during perturbed mitosis." (PMID 33087841, 2020). "CEP55 is a determinant of cell fate during perturbed mitosis in breast cancer." (PMID 32190687, 2020). "In contrast, the knockdown of CEP55 inhibits cell growth in gastric and breast cancer." (PMID 30987631, 2019). "We found that CEP55 is highly expressed in breast cancer with poor clinical outcomes." (PMID 30108112, 2018). "Having established that the combination treatment targeted CEP55‐dependent cells, we treated a panel of 21 breast cancer lines with these agents and found mixed responses, but basal‐like, triple‐negative (TNBC) lines specifically responded to the combination treatment." (PMID 30108112, 2018). "Therefore, we conclude that CEP55 can significantly affect breast cancer tumor progression." (PMID 37887301, 2023). "Similarly, CEP55 was found to be up-regulated in multiple types of cancer and was related to unfavorable prognosis of non-small-cell lung cancer patients and breast cancer patients." (PMID 33101364, 2020). "Furthermore, we showed that CEP55 is a determinant of aneuploid cell fate during perturbed mitosis in breast cancers and could be targeted through MEK1/2-PLK1 inhibition." (PMID 33087841, 2020). "Here, we analyzed the mechanism of how CEP55 controls CIN in ovarian and breast cancer (OvCa) cells." (PMID 39195269, 2024). "Knocking down CEP55 levels delayed epithelial-mesenchymal transition (EMT) and increased cisplatin sensitivity in breast cancer (BC) by inhibiting the P38MAPK and ERK1/2 pathways." (PMID 37887301, 2023).
breast carcinoma (continued). "CEP55 is also part of the PAM50 signature, which is used for breast cancer categorization and prognostic prediction." (PMID 37484531, 2023). "CEP55 deletion can prime premature CDK1/cyclin B activation and mitotic cell death, thus sensitizing breast cancer cells to antimitotic drugs." (PMID 35681641, 2022). "CEP55 (55 kDa) is a centrosomal protein involved in cytokinesis and a known downstream target of FOXM1 oncogene in HNSCC and breast cancer." (PMID 30008265, 2018). "This was consistent with clinical outcomes in these subgroups; breast cancer‐specific survival in the CEP55‐high, CNA‐high group was significantly shorter than cases with lower CEP55 expression and fewer CNAs (P < 0.0001)." (PMID 30108112, 2018). "A recent study involving 3 independent breast cancer microarray datasets containing a total of 699 patients revealed that CEP55 and FOXM1 are amongst the signature prognostic markers which predicts breast cancer outcome." (PMID 19287496, 2009). "Consistent with the notion that CEP55 is a target of FOXM1B, our bioinformatics analysis of published microarray data (GEO Accession: GDS1477) in FOXM1B-knockdown (by siRNA) breast cancer cells showed significant downregulation of CEP55 expression." (PMID 19287496, 2009). "Our data show that a high level of CEP55 increased the CIN rate in OvCa and in breast cancer cells, and since CIN can be caused by dysregulation of spindle MT-dynamics we speculated that CEP55 may be involved in the regulation of spindle MT-dynamics." (PMID 39195269, 2024). "Meanwhile, we found that CEP55, HIST1H2BO, IFI6, KIAA0101, PBK, SPAG5, and SPP1 were significantly upregulated in breast cancer compared to normal samples." (PMID 34055036, 2021). "Further analysis showed that CEP55 was significantly upregulated in triple-negative breast cancers compared to other types of breast cancers, including luminal and HER2-positive cancers, demonstrating CEP55 may have a regulatory role in TNBC." (PMID 34055036, 2021). "Besides, their study also confirmed that CEP55 is a downstream effector of the MEK1/2‐MYC axis, and the high level of CEP55 mRNA and poor clinical prognosis of breast cancer patients related." (PMID 33190424, 2021). "Interaction between miR-144 and centrosomal protein 55 (CEP55) leading to a negative correlation on their expression has been identified in breast cancer." (PMID 33256799, 2020). "Next, we investigated whether expression levels of PIMREG, CEP55, and MTFR2 is related to the expressions of BCSC markers in breast cancer cell lines." (PMID 33718103, 2020). "Interestingly, the analysis of breast cancer datasets revealed that the expression of PICH correlates with that of mitosis-related genes, such as KIF4A, CEP55, MKI67, MELK, BUB1, CENPA, and AURKB." (PMID 31160555, 2019). "This confirmed that CEP55 expression was significantly higher in breast cancer patients compared to normal breast tissue independent of proliferation (P < 0.0001)." (PMID 30108112, 2018). "We demonstrate that six mitotic kinesins and two microtubule-associated non-motor proteins (MAPs) CEP55 and PRC1 are direct transcriptional targets of MuvB, B-MYB and FOXM1 in breast cancer cells." (PMID 28061449, 2017). "The fact that multiple different tumorigenic behaviors were affected by perturbing CEP55 expression suggests that, like other mitotic proteins [e.g., Aurora‐A, Eg5, PLK1, NEK2], it could regulate multiple aspects of breast cancer development." (PMID 30108112, 2018).